RN7SKP39 (RN7SK pseudogene 39)
Gene: Miscellaneous RNA gene on chromosome 10 (28,442,575 to 28,442,896, reverse strand). Ensembl gene ENSG00000222705.
Homologues: Orthologues: chimpanzee 7SK (99% identical), mouse Gm55242 (36% identical). Paralogues in human: 7SK (64% identical), RN7SKP48 (62% identical), RN7SKP185 (62% identical), RN7SKP227 (61% identical), RN7SKP118 (61% identical), RN7SKP178 (61% identical), RN7SKP62 (60% identical), RN7SKP104 (60% identical), RN7SKP174 (59% identical), RN7SKP187 (58% identical), RN7SKP203 (57% identical), RN7SKP76 (57% identical), and 284 more.